CFAP221 (cilia and flagella associated protein 221)
Description:
May play a role in cilium morphogenesis and ciliary function.
Synonyms: PCDP1; FAP221; CILD55
Tractability: Antibody: its Gene Ontology location is reachable by antibodies, with medium confidence.
Gene: Protein-coding gene on chromosome 2 (119,544,432 to 119,662,251, forward strand). Ensembl gene ENSG00000163075.
Subcellular location: Cytoplasm, cytoskeleton, cilium axoneme; Cytoplasm; Cytoplasm, cytoskeleton
Subcellular location (Human Protein Atlas): Connecting piece; Flagellar centriole; Primary cilium; Primary cilium tip
Gene Ontology:
Molecular function: calmodulin binding
Biological process: cilium assembly; motile cilium assembly; cilium movement
Cellular component: axoneme; centriole; ciliary tip; cilium; sperm head-tail coupling apparatus; 9+2 motile cilium; cytoplasm; manchette; cytoskeleton; microtubule cytoskeleton; sperm flagellum
Genetic constraint (gnomAD): Loss-of-function variants: 77 observed, 84.42 expected, observed/expected ratio (o/e) 0.91, 90% interval 0.76 to 1.1. The upper end of that interval is the gene's LOEUF score, 1.1, which puts it in group 4 of 6, group 1 being the genes least tolerant of losing a copy. Missense variants: 820 observed, 845.13 expected, observed/expected ratio (o/e) 0.97, 90% interval 0.92 to 1.03. Synonymous variants: 268 observed, 300.1 expected, observed/expected ratio (o/e) 0.89, 90% interval 0.81 to 0.99.
Gene-disease validity (ClinGen):
ClinGen rates the evidence that CFAP221 causes each of these diseases.
primary ciliary dyskinesia (autosomal recessive): Definitive. A rare, genetically heterogeneous, primarily respiratory disorder characterized by chronic upper and lower respiratory tract disease.
Homologues: Orthologues: chimpanzee CFAP221 (99% identical), macaque CFAP221 (96% identical), rabbit CFAP221 (80% identical), dog CFAP221 (79% identical), pig CFAP221 (79% identical), mouse Cfap221 (72% identical), rat Cfap221 (71% identical), tropical clawed frog cfap221 (41% identical), zebrafish cfap221 (35% identical).
Diseases named in the same sentence as CFAP221 in open-access papers:
CFAP221 is named in the same sentence as 8 diseases in open-access papers, as found by Europe PMC text mining. Sharing a sentence is not in itself a finding about the gene and the disease. The quoted sentences say what the papers report.
Hydrocephalus (4 papers, 2012 to 2019). Hydrocephalus is an active distension of the ventricular system of the brain resulting from inadequate passage of CSF from its point of production within the cerebral ventricles to its point of absorption into the systemic circulation. "Loss of Cfap221 in nm1054 mutant mice results in PCD characterized by hydrocephalus, male infertility and airway abnormalities due to ciliary dysfunction." (PMID 30190587, 2018). "The role played by the genetic background for manifestation of hydrocephalus was previously demonstrated in mouse models of PCD lacking ciliary proteins CFAP221, CFAP54 and SPEF2, respectively." (PMID 31383820, 2019). "We previously demonstrated that mouse models of PCD lacking ciliary proteins CFAP221, CFAP54 and SPEF2 all have hydrocephalus with a strain-dependent severity." (PMID 30190587, 2018).
male infertility (3 papers, 2013 to 2021). The inability of the male to effect fertilization of an ovum after a specified period of unprotected intercourse. "In mice, lack of Cfap221/Pcdp1 causes PCD and male infertility without any obvious ultrastructural abnormalities in the respiratory cilia." (PMID 33809498, 2021).
CFAP221 also shares sentences with these, for which no sentence is quoted: primary ciliary dyskinesia (2 papers); chronic lung disease (1); infection (1); lung carcinoma (1); lung disease (1); Streptococcus pneumoniae infection (1).